ARID1A (AT-rich interaction domain 1A)
Description:
Involved in transcriptional activation and repression of select genes by chromatin remodeling (alteration of DNA-nucleosome topology). Component of SWI/SNF chromatin remodeling complexes that carry out key enzymatic activities, changing chromatin structure by altering DNA-histone contacts within a nucleosome in an ATP-dependent manner. Binds DNA non-specifically. Belongs to the neural progenitors-specific chromatin remodeling complex (npBAF complex) and the neuron-specific chromatin remodeling complex (nBAF complex). During neural development a switch from a stem/progenitor to a postmitotic chromatin remodeling mechanism occurs as neurons exit the cell cycle and become committed to their adult state. The transition from proliferating neural stem/progenitor cells to postmitotic neurons requires a switch in subunit composition of the npBAF and nBAF complexes. As neural progenitors exit mitosis and differentiate into neurons, npBAF complexes which contain ACTL6A/BAF53A and PHF10/BAF45A, are exchanged for homologous alternative ACTL6B/BAF53B and DPF1/BAF45B or DPF3/BAF45C subunits in neuron-specific complexes (nBAF). The npBAF complex is essential for the self-renewal/proliferative capacity of the multipotent neural stem cells. The nBAF complex along with CREST plays a role regulating the activity of genes essential for dendrite growth (By similarity).
Synonyms: BAF250; BAF250A; hOSA1; C1orf4; OSA1; SMARCF1; B120; P270; C10rf4; BM029; CSS2; ELD; MRD14; hELD
Tractability: PROTAC: ubiquitination databases record sites on it; its protein half-life has been measured.
Gene: Protein-coding gene on chromosome 1 (26,693,236 to 26,782,104, forward strand). Ensembl gene ENSG00000117713.
Subcellular location: Nucleus
Subcellular location (Human Protein Atlas): Nucleoplasm
Pathways (Reactome):
Chromatin organization: Formation of neuronal progenitor and neuronal BAF (npBAF and nBAF); Formation of the canonical BAF (cBAF) complex; Formation of the embryonic stem cell BAF (esBAF) complex; RMTs methylate histone arginines
Gene expression (Transcription): RUNX1 interacts with co-factors whose precise effect on RUNX1 targets is not known; Regulation of endogenous retroelements by Piwi-interacting RNAs (piRNAs)
Cell-Cell communication: Positive Regulation of CDH1 Gene Transcription
Developmental Biology: Regulation of MITF-M-dependent genes involved in pigmentation
Gene Ontology:
Molecular function: ATP-dependent chromatin remodeler activity; DNA binding; nuclear receptor binding; protein binding; transcription coactivator activity; nucleosome binding
Biological process: chromatin remodeling; positive regulation of DNA-templated transcription; positive regulation of cell differentiation; positive regulation of double-strand break repair; positive regulation of myoblast differentiation; positive regulation of stem cell population maintenance; positive regulation of T cell differentiation; regulation of G0 to G1 transition; regulation of G1/S transition of mitotic cell cycle; regulation of mitotic metaphase/anaphase transition; regulation of nucleotide-excision repair; regulation of transcription by RNA polymerase II; transcription initiation-coupled chromatin remodeling
Cellular component: chromatin; nucleoplasm; nucleus; SWI/SNF complex; bBAF complex; brahma complex; nBAF complex; npBAF complex
Genetic constraint (gnomAD): Loss-of-function variants: 19 observed, 197.98 expected, observed/expected ratio (o/e) 0.096, 90% interval 0.066 to 0.14. The synonymous counts are far from expectation, so gnomAD's model fits this gene poorly and the ratio says little. Missense variants: 2,585 observed, 2,950.9 expected, observed/expected ratio (o/e) 0.88, 90% interval 0.85 to 0.9. Synonymous variants: 1,376 observed, 1,183.7 expected, observed/expected ratio (o/e) 1.16, 90% interval 1.11 to 1.22.
Gene-disease validity (ClinGen):
ClinGen rates the evidence that ARID1A causes each of these diseases.
Coffin-Siris syndrome (autosomal dominant): Definitive. Coffin-Siris syndrome (CSS) is a rare congenital multi-systemic genetic disorder characterized by aplasia or hypoplasia of the distal phalanx or nail of the fifth digit, developmental delay, intellectual disability, coarse facial features, and other variable clinical manifestations.
Cancer hallmarks: suppression of growth (promotes); cell replicative immortality (promotes); invasion and metastasis (suppresses); escaping programmed cell death (suppresses); genome instability and mutations (suppresses); cell replicative immortality (suppresses)
Homologues: Orthologues: chimpanzee ARID1A (99% identical), macaque ARID1A (99% identical), dog ARID1A (98% identical), pig ARID1A (98% identical), rat Arid1a (97% identical), mouse Arid1a (96% identical), rabbit ARID1A (89% identical), guinea pig ARID1A (81% identical), zebrafish arid1aa (62% identical), zebrafish arid1ab (57% identical), tropical clawed frog arid1a (39% identical), Drosophila melanogaster osa (29% identical), and 1 more. Paralogues in human: ARID1B (51% identical).
Diseases named in the same sentence as ARID1A in open-access papers:
ARID1A is named in the same sentence as 366 diseases in open-access papers, as found by Europe PMC text mining. Sharing a sentence is not in itself a finding about the gene and the disease. The quoted sentences say what the papers report.
ovarian carcinoma (223 papers, 2012 to 2026). A malignant neoplasm originating from the surface ovarian epithelium. "OCCC is a rare subtype of ovarian cancer with high ARID1A gene mutation rates, resulting in genome-wide changes to H3K27Ac levels and histone deacetylase (HDAC) function." (PMID 42041541, 2026). "Genetically, ARID1A mutation is among the most significant changes identified in ovarian cancers with endometriosis, and it has a very high prevalence in clear cell and endometrioid histologies." (PMID 40364006, 2025). "Lastly, a study found that HDAC6 (Histone deacetylase 6) was upregulated in ovarian cancers with ARID1A mutations." (PMID 40429787, 2025). "Loss of ARID1A expression also leads to chemotherapy resistance in a variety of tumors, including lung cancer, ovarian cancer and pancreatic cancer." (PMID 40463905, 2025). "In ovarian cancers with ARID1A mutations, reliance on SNAT2-mediated alanine uptake has been identified as a selective vulnerability." (PMID 41347155, 2025). "For instance, ARID1A-deficient ovarian cancers demonstrate synthetic lethality upon GCLC depletion, underscoring its therapeutic potential." (PMID 41333220, 2025). "In ovarian cancer models, AT-rich interaction domain 1A (ARID1A) mutations impair HDAC complex recruitment, relieve NF-κB inhibition, and activate pro-inflammatory cytokine expression." (PMID 40787446, 2025). "Next, we investigated the response to CX-5461 in mouse models using the ARID1A-deficient ovarian cancer line TOV21G in parallel with the ARID1A-reconstituted cells." (PMID 40938753, 2025). "In ARID1A-mutant ovarian cancers, where loss of the ARID1A chromatin-remodeling gene rewires metabolic programs, tumor cells show heightened reliance on alanine uptake." (PMID 41347155, 2025). "Mutations in the ARID1A gene are frequently detected in ovarian cancers, notably in 46–57% of CCOC and 30% of EC cases." (PMID 41465243, 2025). "The tumor suppressor gene, ARID1A, is a significant driver of mutation across various cancer types, but most prominently in ovarian cancer types." (PMID 40429787, 2025). "ARID1A is frequently mutated in several cancers, including ovarian cancer, where ARID1A mutations/deletions are found in up to 80% of clear cell ovarian cancers (CCC), 40% of endometroid ovarian cancers and 30% of mucinous ovarian cancers." (PMID 38203758, 2024). "Arid1a-deficient ovarian cancer cells have been shown to exhibit altered gene expression patterns, dysregulated cell cycle progression, impaired DNA damage repair, and an enhanced EMT phenotype." (PMID 39123453, 2024). "Ovarian Cancer: The mutation rate of ARID1A in ovarian clear cell carcinoma and ovarian endometrioid carcinomas (OEC) is 46–57% and 30%, respectively." (PMID 38893181, 2024). "ARID1A mutations have been reported to be a poor prognostic factor in various cancers, including ovarian cancer, breast cancer, and gastric cancer." (PMID 38893118, 2024). "Their study demonstrates that inhibiting the EZH2 methyltransferase acts in a synthetic lethal manner in ARID1A-mutated ovarian cancer cells, with ARID1A mutations correlating with the response to the EZH2 inhibitor." (PMID 39471843, 2024). "The immunohistochemical loss of ARID1A in endometriotic lesions has been suggested as a putative prognostic biomarker for ovarian cancer risk." (PMID 39272926, 2024). "In 2010, researchers collected cancerous and normal tissue samples from eight ovarian cancer patients and identified and first reported ARID1A gene mutations by exome sequencing and Sanger sequencing in 57% of patients with clear cell carcinoma of the ovary." (PMID 39697230, 2024).
ovarian carcinoma (continued). "Arid1a mutations have been extensively studied in ovarian cancers and are recognized as drivers of oncogenesis, which also explains the activation status of ovarian cancer signaling in our IPA analysis." (PMID 39123453, 2024). "Yet, ARID1A‐deficient ovarian cancer cells display a resistance to GLS1 inhibition, underscoring a complex metabolic interplay." (PMID 38374872, 2024). "Chemoresistance in epithelial ovarian cancer patients was associated with reduced expression of ARID1A." (PMID 39697230, 2024). "ARID1A mutations are common in ovarian clear cell carcinomas (OCCCs) and endometrioid carcinomas (OECs), leading to loss of ARID1A protein expression and driving ovarian cancer progression." (PMID 38794190, 2024). "In ARID1A-mutated ovarian cancer cells, the expression of PIK3IP1 was reduced, which led to the activation of the PI3K/AKT/mTOR pathway." (PMID 39697230, 2024). "In fact, the inhibition of GCLC significantly decreased GSH in ARID1A-deficient TOV21G ovarian cancer cells, leading to apoptosis (due to increased ROS levels)." (PMID 38203758, 2024). "Everolimus plus bevacizumab shows potential benefits, particularly in ARID1A-mutated ovarian cancer." (PMID 38610698, 2024). "Using an anti-PD-L1 antibody significantly reduced tumor burden in ARID1A-deficient mice and prolonged survival in ARID1A wild-type ovarian cancer mice." (PMID 39697230, 2024). "In the COSMIC database PTEN (11%), PIK3CA (11%) and ARID1A (4%) mutations all occur in BRCA1 mutated ovarian cancer." (PMID 38940864, 2024). "Given the involvement of the catalytic site, the sensitivity of HDAC2 to SAHA was evaluated in preclinical models of ARID1A-mutated ovarian cancers." (PMID 38794190, 2024). "These experiments clearly show that in ovarian cancer, ARID1A protein loss has led to the upregulation of multidrug resistance-associated protein 2 (MRP2) through transcriptional modifications." (PMID 38391958, 2024). "ARID1A is mutated in nearly half of ovarian clear cell carcinoma and around one-third of endometrial and ovarian carcinomas of the endometrioid type." (PMID 38275587, 2023). "One of the most important driver events in ovarian cancer associated with endometriosis is the ARID1A loss-of-function mutation (responsible for chromatin remodelling)." (PMID 38139300, 2023). "Mouse xenografts of ARID1A-deficient ovarian cancers showed greater expression of CD8 and PD-L1, and a superior response to anti-PD-L1 therapy compared to ARID1A-intact tumours." (PMID 38275587, 2023). "ARID1A mutation is considered one of the most important driver events in endometriosis-associated ovarian cancer." (PMID 38029403, 2023). "In vitro, expression of ARID1A in ARID1A-deficient ovarian cancer cell lines reduced cellular proliferation, the percentage of cells in the S phase, and the growth of tumour xenografts." (PMID 38275587, 2023). "unveiling the direct repression of AURKA by ARID1A, studies have been conducted with pan-aurora kinase inhibitors in colon and ovarian cancer cells with ARID1A deficiency, causing chromosomal abnormalities leading to synthetic lethality." (PMID 36890819, 2023). "Previous studies have provided evidence that epithelial mutations in endometriosis or in the endometrium include certain inactivating mutations responsible for ovarian cancer, such as in the ARID1A gene." (PMID 38029403, 2023). "These therapies target either the enhanced proliferative capacity of ovarian cancer cells caused by mutations in ARID1A and SMARCA4 or directly promote apoptosis of the tumour cells to achieve therapeutic goals." (PMID 36883311, 2023). "One study on ovarian cancer found that the relationship between ARID1A loss and CD8+ TILs was confounded by MMR status." (PMID 37366273, 2023). "Although initially, ARID1A suppression in cancer cell line showed increased cisplatin sensitivity, ARID1A deficient ovarian cancer cells showed decreased chemosensitivity to cisplatin." (PMID 36430148, 2022).
ovarian carcinoma (continued). "Endometriomas are a result of ectopic spread of endometrial tissue onto the ovary, forming cysts associated with ovarian cancer development, and numerous reports have observed high rates of ARID1A mutation or loss of expression in endometriomas." (PMID 36153585, 2022). "ARID1A is the most commonly mutated chromatin remodeler gene, exhibiting the highest mutation frequency in endometrium-related uterine and ovarian carcinomas." (PMID 36123603, 2022). "Both findings go together with previously published data on ARID1A mutated tumors, including ovarian cancer, hepatocellular carcinoma, colorectal adenocarcinoma, and non-small-cell lung cancer (NSCLC)." (PMID 35565222, 2022). "Loss of ARID1A in colon and ovarian cancer cells results in epigenetic reprogramming at enhancer regions and reduction of the open chromatin mark, H3K27ac, subsequently leading to loss of transcription of nearest genes." (PMID 36123603, 2022). "ARID1A represents a particularly interesting amiR-4 target since its deletion/mutation sensitises ovarian cancer cells to EZH2 methyltransferase inhibition with the small molecule GSK126 in a synthetic lethal fashion." (PMID 35393414, 2022). "A similar SL interaction to that between BRG1 and BRM has been shown for ARID1A-mutated ovarian cancer cells, which are then dependent on ARID1B." (PMID 36605718, 2022). "ARID1A is frequently mutated across a wide variety of human cancers, including bladder, gastric, pancreatic, and ovarian cancers." (PMID 35852858, 2022). "Loss of ARID1A was proven to be related to high PD-L1 expression in multiple cancers, including non-small cell lung cancer, gastric cancer, ovarian cancer, colorectal cancer, and hepatocellular carcinoma." (PMID 35198440, 2022). "Previous work has highlighted that ARID1A deficiency is related to a mismatch repair phenotype and increased TILs in ovarian cancer mouse models." (PMID 34359755, 2021). "The same mutation was found in atypical endometriosis associated with ovarian carcinoma, so it was estimated that ARID1A mutation occurs at the beginning of the neoplastic transformation of endometriosis." (PMID 33639673, 2021). "In contrast, another study leveraged a mouse ovarian cancer model and demonstrated that ARID1A loss enhances epithelial differentiation and prolongs survival." (PMID 33748136, 2021). "The broad-spectrum tyrosine kinase inhibitor dasatinib was found to arrest the cell cycle during G1 and S phases through increased p21 and retinoblastoma protein expression, which resulted in a robust tumour reduction in ARID1A-mutated ovarian cancer." (PMID 33941852, 2021). "For example, under the condition of inactivation of Apc and Pten, loss of Arid1a impairs the formation of ovarian cancer, and in an Apc-inactivated mouse model of colon cancer, Arid1a is found to be essential for tumorigenesis." (PMID 34671561, 2021). "ARID1A acts as a tumour suppressor, and loss of function has been associated with tumour development in ovarian carcinoma, pancreatic cancer and cervical cancer." (PMID 33941852, 2021). "Ovarian clear cell carcinoma (OCCC) is a rare subtype of epithelial ovarian cancer characterised by a high frequency of loss-of-function ARID1A mutations and a poor response to chemotherapy." (PMID 34359755, 2021). "Over 90% of the ARID1A mutations observed in ovarian cancer are frame-shift or nonsense mutations that result in loss of ARID1A protein expression." (PMID 34070839, 2021). "A more recent study reveals that in ARID1A deficiency ovarian cancer, HDAC6 inhibition synergizes with anti-PD-L1 immune checkpoint blockade, and ARID1A directly repressed the transcription of the CD274 (encoding PD-L1) gene." (PMID 34671561, 2021). "It is unclear why IACS-010759 showed selectivity to ARID1A-deficient ovarian cancer cells, whereas other inhibitors that were tested showed less or no such selectivity." (PMID 33947138, 2021).